RNU6-660P (RNA, U6 small nuclear 660, pseudogene)
Gene: Small nuclear RNA gene on chromosome 5 (16,941,843 to 16,941,951, reverse strand). Ensembl gene ENSG00000201436.
Homologues: Orthologues: chimpanzee U6 (98% identical), macaque U6 (88% identical), pig U6 (73% identical). Paralogues in human: RNU6-1131P (85% identical), RNU6-166P (85% identical), RNU6-242P (84% identical), RNU6-38P (84% identical), RNU6-810P (84% identical), RNU6-1011P (83% identical), RNU6-1330P (83% identical), RNU6-28P (83% identical), RNU6-41P (83% identical), RNU6-44P (83% identical), RNU6-1145P (83% identical), RNU6-11P (83% identical), and 1288 more.